RCN1 (reticulocalbin 1)
Description:
May regulate calcium-dependent activities in the endoplasmic reticulum lumen or post-ER compartment.
Synonyms: RCN; Rcal; PIG20; FLJ37041; HEL-S-84
Tractability: Antibody: UniProt predicts a signal peptide or a membrane-spanning region. PROTAC: ubiquitination databases record sites on it; its protein half-life has been measured.
Gene: Protein-coding gene on chromosome 11 (32,090,971 to 32,105,722, forward strand). Ensembl gene ENSG00000049449.
Subcellular location: Endoplasmic reticulum lumen
Subcellular location (Human Protein Atlas): Endoplasmic reticulum
Pathways (Reactome):
Metabolism of proteins: Post-translational protein phosphorylation; Regulation of Insulin-like Growth Factor (IGF) transport and uptake by Insulin-like Growth Factor Binding Proteins (IGFBPs)
Gene Ontology:
Molecular function: protein binding; calcium ion binding
Cellular component: endoplasmic reticulum; endoplasmic reticulum lumen
Genetic constraint (gnomAD): Loss-of-function variants: 13 observed, 26.87 expected, observed/expected ratio (o/e) 0.48, 90% interval 0.31 to 0.77. The upper end of that interval is the gene's LOEUF score, 0.77, which puts it in group 3 of 6, group 1 being the genes least tolerant of losing a copy. Missense variants: 302 observed, 346.11 expected, observed/expected ratio (o/e) 0.87, 90% interval 0.79 to 0.96. Synonymous variants: 118 observed, 132.07 expected, observed/expected ratio (o/e) 0.89, 90% interval 0.77 to 1.04.
Homologues: Orthologues: chimpanzee RCN1 (100% identical), dog RCN1 (96% identical), pig RCN1 (95% identical), mouse Rcn1 (94% identical), rat Rcn1 (94% identical), guinea pig RCN1 (88% identical), rabbit RCN1 (80% identical), tropical clawed frog rcn1 (73% identical), zebrafish rcn1 (73% identical), Drosophila melanogaster scf (45% identical), Caenorhabditis elegans calu-1 (44% identical). Paralogues in human: CALU (58% identical), RCN3 (55% identical), RCN2 (35% identical), SDF4 (26% identical).
Diseases named in the same sentence as RCN1 in open-access papers:
RCN1 is named in the same sentence as 64 diseases in open-access papers, as found by Europe PMC text mining. Sharing a sentence is not in itself a finding about the gene and the disease. The quoted sentences say what the papers report.
prostate carcinoma (11 papers, 2015 to 2025). A carcinoma that arises from epithelial cells of the prostate gland. "In prostate cancer, RCN1 downregulation induces ER stress, leading to apoptosis in some cells and necroptosis in others, depending on the cell type." (PMID 39828988, 2025). "RCN1 is instead a calcium-binding protein located in the lumen of the ER, while in human endothelial and prostate cancer cell lines, it is plasma membrane-localized." (PMID 40136513, 2025). "In prostate cancer, RCN1 expression increases in the presence of tumor necrosis factor and proinflammatory cytokines in advanced metastasis cancer patients." (PMID 38475805, 2024). "Previous studies have also reported that RCN1 is highly expressed in lung cancer, liver cancer, laryngeal carcinoma, renal cell carcinoma, and prostate cancer, which is consistent with our research findings." (PMID 38713738, 2024). "Deletion of RCN1 in prostate cancer cells significantly inhibits cell viability and leads to endoplasmic reticulum stress." (PMID 37746742, 2023). "RCN1 is upregulated in oral squamous cell carcinoma, prostatic cancer and non-small cell lung cancer." (PMID 35436915, 2022). "Rcn1 was recently reported to be detected on the surface of bone endothelial cells and prostate cancer cells." (PMID 25992960, 2015). "A recent study indicated that Rcn1 also presents on the surface of bone endothelial cells and prostate cancer cells." (PMID 25992960, 2015). "Similarly, it has been confirmed in prostate cancer and nasopharyngeal carcinoma that RCN1 can promote tumor progression by inhibiting cell apoptosis." (PMID 38713738, 2024). "In addition, recent reports have revealed that P4HB and RCN1 acted as tumor-suppressor factors in liver cancer, colon cancer, lung cancer and prostate cancer." (PMID 35436915, 2022). "In addition to localizing in the ER lumen, RCN1 is also expressed on the cell surface, such as bone endothelia cell and prostate cancer cell, and its expression is heterogeneous in each constituent cell of some organs." (PMID 34747128, 2021). "Downregulation of RCN1 inhibited cell proliferation and promote cell death by activating the AKT and PTEN pathways in prostate cancer cells." (PMID 40214031, 2025). "Conversely, downregulation of RCN1 has been found to inhibit cell proliferation and promote cell death by activating the AKT and PTEN pathways in prostate cancer cells." (PMID 37746742, 2023). "Dysregulated RCN1 is found in multiple kinds of cancers including non-small cell lung cancer (NSCLC), prostate cancer, renal cell carcinoma, nasopharyngeal carcinoma, and oral squamous cell carcinoma." (PMID 34976784, 2021).
lung cancer (10 papers, 2019 to 2025). A malignant neoplasm involving the lung. "This includes lung cancer associated genes like CS, which affects tumor drug response, as well as RCN1, which is associated with poor prognosis and tumor progression in lung cancer." (PMID 30894871, 2019). "RCN1 was upregulated in various cancers, such as glioblastoma, non‐small cell lung cancer and nasopharyngeal carcinoma, indicating its involvement in tumorigenesis and invasion." (PMID 40214031, 2025). "In multiple cancers, such as glioblastoma, non‐small cell lung cancer, renal cell carcinoma, hepatocellular carcinoma, and oral squamous cell carcinoma, the overexpression of RCN1 has been observed indicating its involvement in tumorigenesis and invasion." (PMID 37746742, 2023). "In one study, the opposite conclusion was reached, where increasing RCN1 protein levels in cisplatin‐resistant non‐small cell lung cancer with low RCN1 expression levels increased cell sensitivity to cisplatin." (PMID 37746742, 2023). "As RCN1 has recently been shown to correlate with poorer survival in prostate and lung cancer patients we firstly examined its expression profiles in glioma patient samples using the TCGA database." (PMID 33801941, 2021). "RCN1 expression was significantly higher in tumour tissues compared to normal tissues, suggesting that RCN1 may function as an oncogene in lung cancer." (PMID 39828988, 2025). "However, whether RCN1‐mediated bone metastasis of non‐small cell lung cancer (NSCLC) cells was elusive." (PMID 34747128, 2021). "Separate analysis of patients with gastric cancer and non–small cell lung cancer showed that all 4 of the analytes (CLGN, TXD15, HSPA5, and RCN1) were significantly increased in patients who developed clots in both gastric and non–small cell cancer cohorts." (PMID 37651191, 2023). "RCN1 and COL11A1 are highly expressed in lung cancer and promote lung cancer cell proliferation, migration, and invasion." (PMID 35978854, 2022). "The involvement of RCN1 is thus required for lung cancer progression, although its regulatory mechanism is not yet clear." (PMID 34747128, 2021). "However, the specific mechanism by which RCN1 drives lung cancer progression is still not fully understood." (PMID 39828988, 2025).
nasopharyngeal carcinoma (10 papers, 2021 to 2025). A carcinoma arising from the nasopharyngeal epithelium. "RCN1 is a Ca2+ -binding protein, involved in endoplasmic reticulum stress, highly expressed in several malignant tumors like breast cancer, colorectal cancer, naso-pharyngeal carcinoma or non-small cell lung carcinoma associated either with poor prognosis or therapy resistance." (PMID 40975763, 2025). "In particular, RCN1 was implicated in the regulation of drug resistance, and RCN1 knockdown was found to reduce the resistance of nasopharyngeal carcinoma (NPC) cells/tissues to doxorubicin, promoting NPC cell death." (PMID 34663798, 2021). "A recent study found that in nasopharyngeal carcinoma with sensitivity Adriamycin, the down-expression of RCN1 significantly enhanced cell drug-sensitivity." (PMID 35436915, 2022). "RCN1 overexpression has been identified in various tumors, including liver, lung, breast, colorectal, prostate, and nasopharyngeal cancers." (PMID 34663798, 2021). "High RCN1 expression affects the sensitivity of hepatocellular carcinoma cells to sorafenib, while decreasing RCN1 content increases cellular sensitivity to antitumor drugs, such as adriamycin in uterine sarcoma cells and nasopharyngeal carcinoma cells." (PMID 37746742, 2023). "Another study found that reticulocalbin-1 knockdown activated ERS through the activated PERK-CHOP signaling pathway, thus leading to nasopharyngeal carcinoma cell apoptosis." (PMID 34759791, 2021).
renal cell carcinoma (8 papers, 2016 to 2025). "Recently, RCN1 has been demonstrated to be a prognostic marker in various cancers, such as non-small cell lung cancer and renal cell carcinoma." (PMID 34722631, 2021). "Nevertheless, very few data for RCN1 regarding renal cell carcinoma are available." (PMID 40975763, 2025). "Clinical proteomic studies have identified RCN1 as a possible biomarker for renal cell carcinoma." (PMID 39828988, 2025). "Among these proteins, RCN1 was upregulated in all cancer specimens analyzed via proteomics and its expression was further validated using Western blotting and immunohistochemistry, which suggested it as a potential biomarker for renal cell carcinoma." (PMID 38201450, 2023). "Nothing is known about reticulocalbin (RCN3), the protein with highest melanoma expression in the Protein Atlas, but recently, RCN1, a paralog of RCN3, has been found to be a promising tumor marker for renal cell carcinoma." (PMID 27689402, 2016).
glioblastoma (6 papers, 2021 to 2025). The most malignant astrocytic tumor (WHO grade IV). "Our current findings identify that EGFRvIII regulates RCN1 expression and that this novel association promotes cell survival in glioblastoma cells during ER stress." (PMID 33801941, 2021). "To begin to elucidate this potential pro-tumorigenic role, we determined the gene and protein expression of RCN1 in several commercially available parental cell lines, single cell variant sub-populations, stably transfected and patient-derived primary and recurrent glioblastoma cell lines." (PMID 33801941, 2021). "In conclusion, our current findings have identified that the EGFR and EGFRvIII drive RCN1 gene and protein expression which protects glioblastoma cells from apoptosis when challenged with inducers of ER stress." (PMID 33801941, 2021). "Here, we demonstrate that RCN1 expression significantly correlates with poor glioblastoma patient survival." (PMID 33801941, 2021). "Oncomine data mining using the TCGA dataset (n = 542; IDH wt and IDH mutant samples) revealed that RCN1 expression was significantly higher in glioblastoma tissue compared to normal brain tissue." (PMID 33801941, 2021). "EGFRvIII promotes cell survival during ER stress through a RCN1‐dependent mechanism in glioblastoma cells." (PMID 34747128, 2021). "We also demonstrate that glioblastoma cells with expression of EGFRvIII receptor also have high RCN1 expression." (PMID 33801941, 2021). "We propose that sub-populations of cells with EGFRvIII, high wt EGFR and subsequent high RCN1 expression are likely to be more tolerant and better adapted to survive sub-optimal growth conditions often observed in the glioblastoma micro-environment." (PMID 33801941, 2021). "Moreover, overexpression of RCN1 correlates with poor prognosis of non-small cell lung cancer and glioblastoma." (PMID 37723418, 2023). "We used bioinformatic analyses to determine that RCN1 could be an independent factor for the overall survival of Glioblastoma multiform patients." (PMID 34722631, 2021). "Finally, as glucose deprivation and the commonly used glioblastoma patient chemotherapeutic, Temozolomide also induces ER stress we determined the survival of our RCN1 expressing cells in glucose-free media and after temozolomide treatment." (PMID 33801941, 2021). "In vitro experiments indicated that RCN1 promoted cell invasion of Glioblastoma multiform cells." (PMID 34722631, 2021). "Likewise, RCN1 expression was greatest in the primary glioblastoma cell line #41, which naturally expresses the EGFRvIII compared to 4 other primary glioblastoma cell lines that do not express EGFRvIII (#4, #20, #28 and #35)." (PMID 33801941, 2021). "Given that RCN1 correlated with glioblastoma patient survival, we next examined the expression of RCN1 in a series of commercially available and patient-derived primary glioblastoma cell lines established at the Royal Melbourne Hospital." (PMID 33801941, 2021). "Similarly, available TCGA data from OncoLnc consisting of 650 patients illustrated that RCN1 expression was higher in glioblastoma compared to low grade glioma." (PMID 33801941, 2021). "Similarly, the primary glioblastoma cell line #41 (high RCN1 expressing cell) displayed significantly greater cell survival compared to the 4 low RCN1 expressing glioblastoma cell lines (#4, #20, #28 and #35) after treatment with tunicamycin and thapsigargin." (PMID 33801941, 2021). "However, it is unclear as to which receptor tyrosine kinases regulate RCN1 expression and whether RCN1 plays a role in glioblastoma progression." (PMID 33801941, 2021). "Therefore, EGFRvIII expression correlated with RCN1 expression in glioblastoma cell lines." (PMID 33801941, 2021). "The present study aimed to identify the impact of RCN1 on the outcomes of patients with Glioblastoma multiforme (GBM)." (PMID 34722631, 2021).
glioblastoma (continued). "Importantly, TCGA data taken from SurvExpress (n = 148) also revealed that glioblastoma patients with tumors that contained higher RCN1 expression had significantly poorer overall survival compared to patients with glioblastoma tissue with lower RCN1 expression." (PMID 33801941, 2021). "Currently, there is no information about any functional role of RCN1 in glioblastoma progression." (PMID 33801941, 2021). "As we previously demonstrated that EGFRvIII and RCN1 expression correlated with enhanced cell survival under ER stress conditions, we next evaluated whether ATF6 activity varied in high or low expressing RCN1 glioblastoma cells." (PMID 33801941, 2021). "However, the key upstream receptor tyrosine kinase that regulates RCN1 expression and its potential role in cell survival in the glioblastoma setting have not been determined." (PMID 33801941, 2021). "Importantly, cells that expressed EGFRvIII and subsequently showed high RCN1 expression displayed greater cell viability under ER stress compared to EGFRvIII negative glioblastoma cells." (PMID 33801941, 2021). "However, no study to date has evaluated whether EGFRvIII and RCN1 co-operate to promote glioblastoma survival." (PMID 33801941, 2021).
oral squamous cell carcinoma (6 papers, 2021 to 2025). "Recently, a study in oral squamous cell carcinoma also found that RCN1 can regulate M2 macrophage polarization." (PMID 38713738, 2024). "Knockdown of RCN1 exerts a protective effect against oral squamous cell carcinoma." (PMID 40214031, 2025). "However, the exact function of RCN1 in oral squamous cell carcinoma (OSCC) is not fully understood." (PMID 38057406, 2023).
glioma (5 papers, 2021 to 2022). A benign or malignant brain and spinal cord tumor that arises from glial cells (astrocytes, oligodendrocytes, ependymal cells). "Expression levels of risk factors BRCA1, DNM1L, RCN1, HSPB1, RPN2, LRRK2 and SPP1 in high‐grade gliomas were greater than those in lower‐grade gliomas, while the protein expression levels of protective factor PDIA3 were exactly the opposite." (PMID 33611848, 2021). "Furthermore, the correlation analysis indicated that the expression of IFI30, an acknowledged biomarker in glioma, was positively correlated with HLA-DMA, P4HB and RCN1." (PMID 35436915, 2022). "Among them, ARHGAP11A, DRP2, HNRNPA3, KLF10, PAIP1, and RCN1 have not yet been studied in gliomas." (PMID 34434651, 2021).
hepatocellular carcinoma (5 papers, 2021 to 2025). A malignant tumor that arises from hepatocytes. "High levels of RCN1 expression have been associated with sorafenib resistance in hepatocellular carcinoma and doxorubicin resistance in uterine cancer cells." (PMID 37746742, 2023). "RCN1 plays a crucial role in the development of hepatocellular carcinoma by regulating the transport of insulin-like growth factor (IGF), its uptake by IGF binding proteins (IGFBPs), and protein metabolism." (PMID 41465470, 2025). "In hepatocellular carcinoma, RCN1 was found to promote metastasis of hepatocellular carcinoma cells by promoting EMT8." (PMID 38057406, 2023). "The expression of RCN1 has been increasingly observed in various tumour types, including hepatocellular carcinoma, prostate cancer, and highly invasive breast cancer." (PMID 38057406, 2023). "In hepatocellular carcinoma, RCN1 activates c‐MYC signalling via the IRE1α‐XBP1s pathway." (PMID 39828988, 2025).
liver cancer (5 papers, 2021 to 2024). An epithelial or non-epithelial malignant neoplasm that arises from the liver. "RCN1 plays an important role in a variety of solid tumors, including renal, breast, lung and liver cancer, where it regulates tumor invasion and migration." (PMID 38475805, 2024). "However, there are limited studies on the role of RCN1 in tumors, and the role of RCN1 in the development and treatment of liver cancer is still unknown." (PMID 34663798, 2021). "Our research results indicate that knockdown of RCN1 can inhibit EMT in ESCC cells, which is consistent with the research results in liver cancer cells." (PMID 38713738, 2024).
non-small cell lung carcinoma (5 papers, 2021 to 2025). A group of at least three distinct histological types of lung cancer, including non-small cell squamous cell carcinoma, adenocarcinoma, and large cell carcinoma. "The association between high levels of RCN1 and prognostic infaust parameters was also described in non-small cell lung carcinoma (NSCLC) and esophageal squamous carcinoma." (PMID 40975763, 2025). "In addition, RCN1 is molecular marker for the diagnosis and prognosis of non-small cell lung cancer." (PMID 35436915, 2022). "It has been found that RCN1 is involved in breast cancer, colorectal cancer, liver cancer, kidney cancer, and non-small cell lung cancer." (PMID 34722631, 2021).
colorectal cancer (4 papers, 2015 to 2025). A primary or metastatic malignant neoplasm that affects the colon or rectum. "Besides, RCN1 is highly expressed in invasive breast cancer cell and colorectal cancer cell, suggesting that RCN1 is implicated in tumor cell invasiveness." (PMID 37723418, 2023). "Rcn1 expression is upregulated in limb-girdle muscular dystrophy as well as a number of cancerous cell lines, such as invasive breast cancer and colorectal cancer." (PMID 25992960, 2015).
breast carcinoma (3 papers, 2023 to 2025). "In breast cancer cells, RCN1 forms a complex with PIGX and RCN2 that negatively regulates the expression of ZIC family member 1 (ZIC1) and EH domain‐containing protein 2 (EHD2), promoting breast carcinogenesis." (PMID 37746742, 2023).
epidermoid carcinoma (3 papers, 2021 to 2025). "From squamous carcinoma (esophageal and oral) is known that the knockdown of RCN1 inhibits the polarization of M2 macrophages." (PMID 40975763, 2025).